BACH2 (BACH transcriptional regulator 2)
Diseases named in the same sentence as BACH2 in open-access papers (continued):
Sharing a sentence is not in itself a finding about the gene and the disease.
viral infection (7 papers, 2017 to 2025). "Acute viral infections typically induce Type 1 responses, and it was of interest to assess whether Bach2 deficiency altered the effect of LCMV infection on Tregs and whether Treg-specific Bach2 deficiency led to enhanced T cell responses to an LCMV infection." (PMID 36033397, 2022). "However, the loss of BACH2 caused enhanced CD8+ T cell apoptosis 5–10 days after viral infection, indicating a different role in T cells." (PMID 30459773, 2018). "Bach2 regulates CD8 + T cell differentiation by controlling the access of AP-1 factors to enhancers The regulation of CD8 + T cells by Bach2 in response to viral infection lays the foundation for further studies on how Bach2 controls CD8 + T cell differentiation and function." (PMID 38459508, 2024). "Fourth, loss of Bach2 in Tregs does not affect Type 1 immunity to systemic and mucosal viral infections." (PMID 36033397, 2022). "An emerging theme from our studies is that loss of Bach2 expression in Tregs does not affect TH1 responses to systemic or mucosal viral infections." (PMID 36033397, 2022). "Further, we show that loss of Bach2 in Tregs does not affect the development of TC1/TH1 cells during mucosal or systemic viral infections but instead augments the differentiation of IL-5 and IL-13-producing TH2 cells during fungal allergen-induced inflammation in the lungs." (PMID 36033397, 2022). "As summarized in this review, Tfh cell-related transcription factors including Bcl6, IRF4, STAT1/STAT4/STAT5, T-bet, TCF-1, LEF-1, TOX2, Bach2, FOXP1, and KLF2 are all involved in the virus infection." (PMID 32766317, 2020). "Based on these reports, we may speculate that rare long-lived cell clones with BACH2 or STAT5B activating viral insertions and harboring an infectious viral genome could exist and sustain viral infection during years." (PMID 28887441, 2017).
B cell lymphoma (6 papers, 2009 to 2025). "When Namalwa cells, derived from human B cell lymphoma cell, were treated with hemin in the presence of cycloheximide to block new synthesis of proteins, BACH2 protein was decreased." (PMID 39758820, 2025). "We report that the Bach2 gene is a target of proviral integrations in B-cell lymphomas induced by murine leukemia virus." (PMID 19159451, 2009). "We here address patterns of insertional mutagenesis and expression of Bach2 is a murine retroviral model of B-cell lymphoma induction." (PMID 19159451, 2009). "Our study has therefore allowed the description of a previously unknown role for c-Rel in the prevention of B-cell lymphoma development by regulating the expression of Bach2." (PMID 26522720, 2016). "Such differential expression of protein isoforms with distinct functions may explain why the Bach2 gene, previously suggested to be a tumor suppressor may be up-regulated in B-cell lymphomas." (PMID 19159451, 2009). "BACH2 has been shown to have a significant inhibitory effect on cellular proliferation, and deletion of BACH2 expression may contribute to the development of B-cell lymphomas, including BL." (PMID 38482011, 2024).
Crohn disease (6 papers, 2013 to 2025). A gastrointestinal disorder characterized by chronic inflammation involving all layers of the intestinal wall, noncaseating granulomas affecting the intestinal wall and regional lymph nodes, and transmural fibrosis. "Most notably, variations in the BACH2 gene are associated with Crohn’s disease." (PMID 33903979, 2021). "We found significant differences in the methylation levels in the MGAT3 and BACH2 genes between both Crohn’s disease and ulcerative colitis when compared to HC." (PMID 29991969, 2018).
diabetes (6 papers, 2013 to 2023). "In addition a further 9 genes were associated with diabetes (p < 0.006), including BACH2 (q < 1.5 × 10-10), the second most significantly age-associated gene in this study." (PMID 23941278, 2013). "As we have learned, some of the diabetes susceptibility genes e.g., GLIS3, PTPN2, BACH2 and Cathepsin H, regulate Bim expression." (PMID 26405162, 2015). "The free energy of the interaction of miR-466 and ID00436.3p-miR with mRNA of the BACH2, FASLG, HEMGN and IGF2R genes, which are involved in diabetes diseases, is −105 ± 1 kJ/mole with GU repeats in the 3′UTR." (PMID 35627185, 2022). "It should further be noticed that genes of importance for islet function and diabetes such as PDX1, TCF7L2, FOXA2, FOXO1, NEUROD1 and BACH2 have C1, C3 or both these sites at their ATAC-seq open chromatin regions." (PMID 31123324, 2019).
Hashimoto thyroiditis (6 papers, 2014 to 2025). An autoimmune disorder caused by the production of autoantibodies against thyroid tissue. "BACH2 had previously been identified as harbouring susceptibility variants in both Graves’ and Hashimoto’s thyroiditis patients in a smaller UK population." (PMID 38108994, 2024). "A recent candidate gene analysis associated the BACH2 locus with an increased risk of AITD, including Hashimoto's thyroiditis and Graves' disease." (PMID 24586183, 2014). "The dysregulation of immune tolerance mechanisms, specifically the BACH2/PDCD5-FOXP3 pathways and Tregs, may be shared underlying factors between MS and Hashimoto’s thyroiditis." (PMID 40900203, 2025).
rheumatoid arthritis (6 papers, 2018 to 2025). A chronic, systemic autoimmune disorder characterized by inflammation in the synovial membranes and articular surfaces. "The absence of T cell BACH2 may also promote changes in the regulation of apoptosis, as the JNK/AP-1 pathway has been associated with apoptosis in synovial cells in rheumatoid arthritis, and several studies have implicated BACH2 in promoting apoptosis." (PMID 30459773, 2018).
Graves disease (5 papers, 2011 to 2021). Graves' disease is an autoimmune disorder that leads to overactivity of the thyroid gland (hyperthyroidism).It is caused by an abnormal immune system response that causes the thyroid gland to produce too much thyroid hormones. "The current study provides insight into this phenomenon by showing that specific loci associated with TPOAbs and (subclinical) hypothyroidism, i.e. MAGI3 and BACH2, are also associated with Graves' hyperthyroidism in an independent case-control study." (PMID 24586183, 2014). "The MAGI3 and BACH2 variants were associated with an increased risk of hyperthyroidism, which was replicated in an independent cohort of patients with Graves' disease (OR: 1.37, 95% CI 1.22–1.54, P = 1.2×10−7 and OR: 1.25, 95% CI 1.12–1.39, P = 6.2×10−5)." (PMID 24586183, 2014). "In the present report we illustrate that this strategy is successful with the identification of two new candidate genes for Graves' disease susceptibility, BACH2 and UBASH3A." (PMID 21829393, 2011). "Both were associated with an increased risk of Graves' disease (MAGI3- rs1230666: OR, 1.37 [95% CI, 1.22–1.54]; P = 1.2×10−7;BACH2- rs10944479: OR, 1.25 [1.12–1.39]; P = 6.2×10−5)." (PMID 24586183, 2014). "TPOA are commonly detected in Graves' disease patients and, therefore, the TPOA- associated SNPs located in the genes RASGRP1, UBASH3A and BACH2 that have not been previously tested for Graves' disease association are strong Graves' disease candidates." (PMID 21829393, 2011).
acute lymphoblastic leukaemia (4 papers, 2016 to 2021). "Interestingly, the ratio of BACH2:BCL6 expression levels represent a significant predictor of outcome in acute lymphoblastic leukaemia (ALL)." (PMID 35008187, 2021).
allergic disease (4 papers, 2019 to 2025). An immune response that occurs following re-exposure to an innocuous antigen, and that requires the presence of existing antibodies against that antigen. "Previous studies suggested that BACH2 is associated with numerous autoimmune and allergic diseases in humans by inducing excessive pathogenic Tfh cells, which is opposite to results observed in mice." (PMID 34032001, 2021). "Genetic polymorphisms in the BACH2 gene locus are associated with numerous autoimmune and allergic diseases in human." (PMID 31552021, 2019). "Notable genes associated with allergy, immune responses, and inflammation were found (LCK, BACH2, SATB1, LIME1, KSR1, BCL11B, TCF1, and EVL)." (PMID 41394805, 2025).
colitis (4 papers, 2019 to 2023). Inflammation of the colon. "Notably, in a model of chemically-induced colitis, loss of Bach2 in Tregs protected against colitis." (PMID 36033397, 2022). "Notably, both in DSS colitis and in steady state, we observed reduced numbers of intestinal RORγt+ Treg cells in Bach2fl/flFoxp3Cre mice, suggesting that Bach2 plays a role in maintaining pTreg cells." (PMID 31937752, 2020). "In contrast, mice with Bach2-deficient Treg cells were largely protected from colitis and showed an overall reduced disease score compared with control mice, suggesting protection due to improved Treg cell function in the absence of Bach2." (PMID 31937752, 2020). "In addition, Bach2 supports the suppressive capacity of Treg cells, as a loss-of-function study demonstrated that Bach2-deficient Treg cells failed to prevent disease in a colitis model." (PMID 30962454, 2019).
hypothyroidism (4 papers, 2014 to 2023). Abnormally low levels of thyroid hormone. "The MAGI3 and BACH2 variants were associated with an increased risk of hyperthyroidism, and the MAGI3 variant was also associated with an increased risk of hypothyroidism." (PMID 24586183, 2014). "The MAGI3 SNP was associated with a substantially increased risk of hypothyroidism, and the BACH2 SNP showed a borderline significant association (P = 0.011) with a higher risk of increased TSH levels, which includes subjects with subclinical and overt hypothyroidism." (PMID 24586183, 2014).
inflammatory bowel disease (4 papers, 2018 to 2022). A spectrum of small and large bowel inflammatory diseases of unknown etiology. "Therefore, Bach2 may be a potential candidate for therapy of inflammatory bowel diseases." (PMID 32082072, 2019).
lung disease (4 papers, 2018 to 2025). "For example, Bach2 knockout mice developed a Th2 cell-dependent lung disease, associated with enhanced Th2 cell cytokine production and lung inflammation, indicating a requirement for BACH2 in controlling Th2 cell differentiation and/or tissue recruitment." (PMID 30459773, 2018). "Additionally, Bach2 deficiency in all T cells leads to spontaneous development of TH2-driven lung disease." (PMID 36033397, 2022). "One limitation of the constitutive Bach2 knockout model used in this study was the severe phenotype of the mice, which had to be euthanized after 18 weeks to minimize suffering from the previously characterized lung disease." (PMID 41169388, 2025). "Further, loss of Bach2 in all T cells also leads to aberrant TH2 immunity and lung disease." (PMID 36033397, 2022). "Treg-specific Bach2 deficiency did not lead to the unprovoked development of eosinophilic crystalline pneumonia or TH2-driven lung disease for at least until 8-9 months of age." (PMID 36033397, 2022). "Based on pathway enrichment analysis, genes altered in BPD blood cells were mainly enriched in cell cycle regulation and arrest (e.g., PPP2CA, RBL2, CENPU, CCNY, CDK6) and pulmonary disorder and developmental disorders (e.g., AGER, ITGA6, CA4, BACH2, IGFBP2, BMPR2, SKI, DAB2)." (PMID 35484630, 2022). "We observed that Treg-specific Bach2 deficiency did not result in overt lung pathology, which suggested that Bach2 expression in conventional T cells is sufficient to protect against spontaneous TH2 lung disease." (PMID 36033397, 2022).
vitiligo (4 papers, 2014 to 2024). Generalized well circumscribed patches of leukoderma that are generally distributed over symmetric body locations and is due to autoimmune destruction of melanocytes. "Ongoing research explores the interplay between vitiligo and BACH2, a gene identified in GWAS as potentially linked to the condition." (PMID 38891024, 2024). "The GWAS-MA for vitiligo showed suggestive association of SNPs (nt 90941239-91915693) spanning BACH2, particularly rs3757247, confirmed by the replication study and overall meta-analysis." (PMID 26870082, 2016). "Though no direct causal relationship has been definitively established, there is a growing curiosity surrounding BACH2’s role in vitiligo’s pathogenesis, particularly regarding immune system dysregulation and autoimmune mechanisms." (PMID 38891024, 2024). "GWAS-MA has identified vitiligo-associated loci TG/SLA and BACH2 in European-derived white (CEU) population." (PMID 26870082, 2016).
Burkitt lymphoma (3 papers, 2009 to 2016). A rare form of malignant mature B-cell non-Hodgkin lymphoma. "In the Burkitt lymphoma cell line Raji, loss of Bach2 expression at both the mRNA and protein levels was attributed to Epstein-Barr virus (EBV) genome integration into the host Bach2 gene." (PMID 19159451, 2009). "BACH2, paradoxically, is a suspected tumor suppressor in CML and Burkitts lymphoma." (PMID 24827933, 2014).
chronic pancreatitis (3 papers, 2019 to 2025). A chronic inflammatory process causing damage and fibrosis of the pancreatic parenchyma. "In CD4+ T lymphocytes from chronic pancreatitis tissues, the knockdown of the transcription factor Bach2 downregulates OTUD5 expression." (PMID 37190070, 2023). "The exposure of BTB and CNC homologous 2(Bach2)-silenced CD4+ T lymphocytes to chronic pancreatitis tissue extracts leads to a decrease in OTUD5 and increased Th17 cell differentiation." (PMID 37190070, 2023).
enteropathy (3 papers, 2021 to 2023). "In some cases, these findings provide clues to the pathogenesis of the complications in CVID, such as mutations in CTLA4, LRBA and BACH2 which have been identified in subjects with severe enteropathy." (PMID 37711607, 2023).
gastric cancer (3 papers, 2020 to 2021). A primary or metastatic malignant neoplasm involving the stomach. "In addition, BACH2 is an epigenetic target for inhibiting the proliferation of gastric cancer cells." (PMID 32892482, 2020). "Therefore, studying the expression of BACH2 may provide newer insights for the prognosis and design of immune-based therapies in MSI-H gastric cancer." (PMID 33316777, 2020).
lung carcinoma (3 papers, 2021 to 2025). "BACH2 has been reported as the immunosuppressive factor in the lung cancer, which indicates poor prognosis." (PMID 40057671, 2025). "BACH2 can limit NK cell maturation under conditions of weak stimulation, maintaining numbers of undifferentiated NK cells such that knocking out BACH2 in NK cells can lead to cytotoxic NK cell accumulation within tissues, more effectively protecting against lung cancer metastasis." (PMID 40070829, 2025). "The currently available literature indicates that exosomal miR-210 is involved in the regulation of various lung cancer-related signaling molecules and pathways, including STAT3, TIMP-1, KRAS/BACH2/GATA-3/RIP3, and PI3K/AKT." (PMID 34440422, 2021).
mantle cell lymphoma (3 papers, 2020 to 2021). Mantle cell lymphoma is a rare form of malignant non-Hodgkin lymphoma affecting B lymphocytes in the lymph nodes in a region called the ``mantle zone''. "BACH2 expression varies in different tumours; CD19+ B cells from mantle cell lymphoma patient samples showed reduced BACH2 levels." (PMID 32892482, 2020).
melanoma (3 papers, 2020 to 2022). A malignant, usually aggressive tumor composed of atypical, neoplastic melanocytes. "Our study shows that, in mice, Bach2 functions as a checkpoint to restrain NK cell cytotoxicity and Bach2 deficiency leads to enhanced NK cell-mediated control of B16 melanoma metastases." (PMID 36190189, 2022). "This central function has major implications in cancer immunity, since tumor growth is significantly delayed in Bach2-null mice transplanted with melanoma or thymoma cells, which is associated with reduced Treg cell accumulation in the tumor." (PMID 33143070, 2020). "Similarly, conditional Bach2 or Senp3 ablation in Treg cells leads to enhanced anti-tumor immunity and delayed progression of transplanted colon cancer and melanoma, respectively, demonstrating a Treg-cell-intrinsic function of Bach2 in cancer." (PMID 33143070, 2020).
prostate carcinoma (3 papers, 2011 to 2019). A carcinoma that arises from epithelial cells of the prostate gland. "MIR193A is noticed to be upregulated in prostate cancer tissues and cell lines, with significant suppression of cell apoptosis induced by oxidative stress by targeting Bach2." (PMID 31523496, 2019). "In particular, RegNetB identified the regulators PAX4, BACH1, BACH2, MAZ and TAF8 as playing a central role in this prostate cancer gene expression data set." (PMID 21682879, 2011).
autoimmune Addison's disease (2 papers, 2016 to 2025). "We performed a two-stage case control association study in UK and Norwegian cohorts and found that allelic variability in BACH2 locus confers susceptibility to autoimmune Addison's disease." (PMID 27680876, 2016).
coronary artery disease (2 papers, 2019 to 2025). "However, long-term downregulation of BACH2 in Treg cells of patients with coronary artery disease may be harmful given the essential role of BACH2 in Treg cell formation." (PMID 40461772, 2025).
epithelial ovarian cancer (2 papers, 2019 to 2021). "These genes included acetylcholinesterase (ACHE) and basic leucine zipper transcription factor 2 (BACH2) whose functions in ovarian cancer remain poorly understood." (PMID 30791431, 2019). "The expression of ACHE and BACH2 proteins was also found to be elevated in ovarian cancer tissue specimens, compared with benign tumors or normal ovaries, and associate with worse patient outcomes." (PMID 30791431, 2019). "In epithelial ovarian cancer, miR-130b inhibited cancer cell migration and invasion via TGF-β signaling, and in nasopharyngeal carcinoma, miR-130a promoted apoptosis by targeting BACH2." (PMID 35187064, 2021).